RASAL1 (RAS protein activator like 1)
Diseases named in the same sentence as RASAL1 in open-access papers (continued):
Sharing a sentence is not in itself a finding about the gene and the disease.
cancer (23 papers, 2011 to 2025). A tumor composed of atypical neoplastic, often pleomorphic cells that invade other tissues. "Eight cancer types with copy number loss at a frequency > 20% showed a significant correlation between mRNA level and copy number of RASAL1, demonstrating the functional significance of RASAL1 copy loss." (PMID 39032134, 2024). "We identified the MEST-PURA-SRCIN1/RASAL1-ERK-snail signaling cascade as an important mechanism underlying cancer metastasis." (PMID 37149929, 2023). "In conclusion, we have identified the MEST-PURA-SRCIN1/RASAL1-ERK-snail signaling cascade as a key mechanism underlying cancer metastasis." (PMID 37149929, 2023). "For these diverse cancer types with RASAL1 epigenetic silencing, often associated with Ras-driven carcinogenesis, the added loss of the suppressor potentially super-activates the Ras signaling axis." (PMID 31627186, 2019). "De-methylating activity was less effective than 5′-Azacytidine, which caused Rasal1 de-methylation at optimum dosage within 24 h, similar to what has been observed in cancer cells." (PMID 25717475, 2015). "Transcriptional suppression of RASAL1 through aberrant promoter methylation contributes to endothelial to mesenchymal transition which was an important source of cancer-associated fibroblasts (CAFs), which are known to facilitate tumor progression in several ways." (PMID 31847887, 2019). "Therefore, we suggest that, similarly to other cancers characterized by RASAL1 mutations, the loss of this tumor suppressor might promote BC development." (PMID 32906649, 2020). "Dual Rasal1‐Pten defects thus form a robust genetic mechanism to promote cancer aggressiveness through cooperatively activating the PI3K‐AKT pathway." (PMID 39032134, 2024). "An accelerated decline in disease‐specific survival or disease progression‐free survival was also observed with RASAL1 alterations in some cancer types when individually analyzed." (PMID 39032134, 2024). "This is even more clear with the case of the genetic duet of RASAL1 and PTEN alterations, which was robustly associated with disease recurrence and disease‐specific mortality in many cancers in the present study." (PMID 39032134, 2024). "and that epigenetic RASAL1 silencing leads to fibroblast activation and fibrogenesis, similar to the ability of cancer cells to proliferate in a growth factor-independent manner following RASAL1 silencing." (PMID 37056286, 2023). "Among these, it is worth mentioning the Ras GTPase-activating protein (GAP) Ras protein activator-like 1 protein (Rasal1), which inhibits Ras/MAPK activation and whose reduced expression in cancer cells is linked to tumor progression." (PMID 34681881, 2021). "ROS1 and RASAL1 are two genes with established roles in tumor development and progression in different types of cancer." (PMID 32906649, 2020). "In the Human Protein Atlas NPL, POLN and RASAL1 showed generally an increased expression in most cancer tissues." (PMID 32906649, 2020). "In the 131 independent BC patients, we detected mainly RASAL1 loss-of-function variants, in concordance with a tumor suppressor role of RASAL1 in cancer." (PMID 32906649, 2020). "RASAL1 has been identified as a tumor suppressor, frequently silenced by promoter hypermethylation in numerous cancer types." (PMID 31627186, 2019). "Recently, RASAL1 has been shown to exert anti-neoplastic effects in many cancer cells including cancers of the gastric, oesophagogastric adenocarcinoma, thyroid and liver." (PMID 31847887, 2019). "Despite its importance in the transformation of cells, the role of Rasal1 in T-cell activation and cancer immunotherapy has yet to be explored." (PMID 31641113, 2019). "As a negative modulator of the RAS signaling pathway by functioning as a Ras-GAP that catalyzes RAS inactivation, RASAL1 has been suggested to be a candidate tumor suppressor gene and impacts the profile of cancer in recent years." (PMID 31847887, 2019).
cancer (continued). "RASAL1 is a member of ras GTPase-activating protein families and recently reported to be a tumor suppressor gene in several types of cancer." (PMID 28499406, 2017). "Here, we used human cancer genetic and clinical data to explore the broad tumor suppressor gene candidacy of RASAL1 and its clinical significance and used genetic mouse models to functionally confirm and establish its tumor suppressor function—particularly with respect to the PTEN status." (PMID 39032134, 2024). "Analysis in the 9924 cancers for 724 known cancer genes in the Cancer Gene Census (CGC) database revealed that mutations in 11 genes, whose mutation frequencies were > 5%, concurred with RASAL1 alterations (adjusted P < 1.00E‐05, Fisher's exact test)." (PMID 39032134, 2024). "Among various RasGAPs, only RASAL1 expression was decreased in cancer." (PMID 39032134, 2024). "However, in other studies RASAL1 was found significantly downregulated in cancer, whereas its overexpression blocked cancer progression." (PMID 32906649, 2020). "RASAL1, has recently been identified as an important tumor suppressor for numerous cancers." (PMID 33817145, 2019). "Here, the authors show that Rasal1, a GTPase-activating protein, binds and inhibits signaling downstream of the T Cell Receptor complex and that consistently, its reduced expression enhances anti-tumor T-cell responses in two syngeneic cancer mouse models." (PMID 31641113, 2019). "RASAL1 alterations cause constitutive activation of RAS, initiating the PI3K pathway signaling, which will be unconstrained in the presence of defective PTEN, thus constantly activating the PI3K pathway signaling and driving the aggressiveness and poor clinical outcomes of human cancer." (PMID 39032134, 2024). "Importantly, we demonstrate for the first time that circulating methylated RASAL1 CpG island promoter fragments correlate with degree of intrarenal RASAL1 methylation and degree of fibrosis, similar to increased levels of methylated CpG fragments which can be detected in cancer patients." (PMID 25717475, 2015). "The MEST-PURα interaction is pivotal for the activation of SRCIN1/RASAL1-ERK-Snail signaling and cancer metastasis." (PMID 39844051, 2025). "The binding of MEST to PURα blocked the physical interaction between PURα and the promoters of SRCIN1 and RASAL1, leading to the activation of ERK signaling and cancer metastasis." (PMID 39844051, 2025). "Here, we investigated the oncogenic and clinical impacts of genetic alterations of RASAL1, particularly when coexisting with genetic alterations of the gene for phosphatase and tensin homolog (PTEN), in 9924 cancers of 33 types in the TCGA database." (PMID 39032134, 2024). "Taken together, our results demonstrate that MEST regulates SRCIN1/RASAL1-ERK-snail signaling and cancer metastasis in a PURA-dependent manner." (PMID 37149929, 2023).
cancer (continued). "In gastric cancer, the upregulation of miR-107 and miR-130b-5p was shown to promote proliferation, migration, and invasion of cancer cells, partially via reduction of their respective targets NF1 and RASAL1." (PMID 33096593, 2020). "RAS protein activator like-1 (RASAL1) exists in numerous human tissues and has been commonly demonstrated to act as a tumor suppressor in several cancers." (PMID 33817145, 2019). "Among the top 10 DRGs identified from TCGA-STAD dataset, six are GC related (E2F1, AK1B10, CEBPA, PTK7, RASAL1, GKN), and three are cancer related (DPCR1, GGT6, RAB25)." (PMID 29745833, 2018). "Given that RASAL1 and PTEN normally cooperatively constrain the PI3K pathway signaling, at an upper and lower step, respectively, it is plausible to see this robust cooperation of RASAL1 and PTEN alterations in activating the PI3K pathway and promoting cancer aggressiveness." (PMID 39032134, 2024). "Thus, the unique concurrent RASAL1 and PTEN defects drive oncogenesis and cancer aggressiveness by cooperatively activating the PI3K–AKT pathway." (PMID 39032134, 2024). "Specifically, 52.97% of the cancers with RASAL1 alterations versus 33.07% of the cancers without RASAL1 alterations had PTEN alterations (P = 4.02E‐47)." (PMID 39032134, 2024). "Kaplan–Meier analyses of all cancers showed an accelerated decline in disease progression‐free survival with RASAL1 alterations compared with that without RASAL1 alterations (HR = 1.28, P < 0.001)." (PMID 39032134, 2024). "Sequencing data for ROS1 and RASAL1 genes were retrieved in silico from WES analysis of 197 Italian subjects with no reported cancer history, who were selected as controls." (PMID 32906649, 2020). "Thus, concurrent RASAL1 and PTEN alterations cooperatively aggravated cancer aggressiveness." (PMID 39032134, 2024). "Besides, we identified several canonical cancer-associated genes that were not enriched in the significantly disturbed pathways, such as ADAMTS9, HIC1, RASAL1, in both the methylation statuses and expression data." (PMID 22140553, 2011).
tumor (23 papers, 2011 to 2025). "The RASAL1 gene is a tumor suppressor gene that encodes the RASAL1 protein, a member of the Ras-GAP family with GTPase activity and converts active RAS-GTP to inactive RAS-GDP, regulating normal cell growth, differentiation and proliferation." (PMID 37056286, 2023). "Our findings identify ZAP-70-associated Rasal1 as a new negative regulator of T-cell activation and tumor immunity." (PMID 31641113, 2019). "Copy loss and mutations of RASAL1 were mutually exclusive (P = 0.0019, Fisher's exact test), being 12.91% and 1.52%, respectively, suggesting their equal deleterious nature expected for a tumor suppressor gene." (PMID 39032134, 2024). "This study provides strong and broad genetic, clinical, and functional evidence establishing RASAL1 as another prominent general tumor suppressor gene, after PTEN, in the PI3K pathway." (PMID 39032134, 2024). "The downregulation of other TCR signaling intracellular mediators such as SHP-1, DGKs, PTPN2286 or RASAL1 also led to better control of tumor growth by genetically-modified T cells in preclinical models." (PMID 33287392, 2020). "RASAL1 inhibited tumor growth in xenograft nude mice models and shows inhibitory effect of SCD1 expression in vivo." (PMID 31847887, 2019). "Tumor weight was reduced from a mean of 580 to 370 mg in mice with Rasal1 KD T cells relative to scrambled RNAi." (PMID 31641113, 2019). "Lastly, we showed that the adoptive cell transfer of T cells expressing Rasal1 siRNA limited the growth of two different tumor types in mice." (PMID 31641113, 2019). "RT-qPCR and Western blot analysis showed that RASAL1 expression was increased in the tumor tissues of RASAL1 group compared with that of the control group, which decreased the SCD1 mRNA and protein levels." (PMID 31847887, 2019). "Based on this mechanism, lower expression of RASAL1 should be found in tumor samples as up-regulated RASAL1 suppresses tumor progression." (PMID 33817145, 2019). "These all further support RASAL1 being a prominent tumor suppressor gene." (PMID 39032134, 2024). "The significance of the prominent tumor suppressor gene for RAS protein activator‐like 1 (RASAL1) could be better understood by combined genetic, clinical, and functional studies." (PMID 39032134, 2024). "Activated RASAL1 pathway could inhibit tumor growth by directly targeting the RASAL1 3’-UTR in sorafenib-sensitized hepatocarcinoma cells." (PMID 33817145, 2019). "Rasal1 inhibition could improve adoptive immunotherapies using tumor antigen specific T cells." (PMID 31641113, 2019). "We next assessed whether Rasal1 represented a potential therapeutic target in anti-tumor immunity." (PMID 31641113, 2019). "For instance, the upregulation of WNT10A, RASAL1, CAMK2B, and SALL4 suggests their involvement in tumor-promoting processes, such as cell proliferation, migration, and immune evasion." (PMID 40797277, 2025). "In a recent study the GTPase-activating protein (GAP) Rasal1, which inhibits ZAP-70, has been identified to suppress anti-tumor immune-responses." (PMID 33194762, 2020). "Here, we identify the GTPase-activating protein (GAP) Rasal1 as a novel TCR-ZAP-70 binding protein that negatively regulates T-cell activation and tumor immunity." (PMID 31641113, 2019). "Yet, broad genetic, clinical, and definitive functional evidence establishing RASAL1 as a prominent general human tumor suppressor gene is lacking." (PMID 39032134, 2024). "Our analysis identified seven tumour suppressor genes (ITGA7, SLC45A1, TPPP, SCN4A, GIPR, SOGA3 and RAB6B) and six oncogenes (SAT1, SERPINE1, UPK2, SYT12, RASAL1 and CDH3) with significant false discovery rate (FDR)-adjusted P values (q-value) of less than 0.05." (PMID 38429478, 2024). "The RAS GTPase-activating protein (Ras-GAP) gene RASAL1 has been demonstrated as a tumor suppressor gene which act as a negative modulator of the RAS signaling pathway by catalyzing RAS inactivation." (PMID 31847887, 2019).
tumor (continued). "Besides, we found that RAS protein activator like 1 (RASAL1) and keratin 17 (KRT17) were clearly hypomethylated in the promoter region and over-expressed in the tumor samples compared to the controls." (PMID 22140553, 2011). "Likewise, RASAL1 promoter DNA hypermethylation in gastric cancer tumor tissues were greater than that in paired adjacent non-tumor tissues." (PMID 31627186, 2019). "Antagonizing ZAP-70 inhibition by siRNA against Rasal1 increased the number of CD8+ tumor-infiltrating T-cells expressing granzyme B and interferon gamma (no ‘1') and enhanced tumor killing." (PMID 33194762, 2020).
neurological disorders (1 paper, 2024). "As well as Rasal1’s role in learning and memory deficits coinciding with neurological disorders." (PMID 38246997, 2024).
renal disease (1 paper, 2022). "The role of RASAL1 hypermethylation in the pathogenesis of kidney fibrosis has been proved in other models of nephropathy, ureteral obstruction, and nephrotoxic serum nephritis." (PMID 35806113, 2022).
RASAL1 also shares sentences with these, for which no sentence is quoted: benign colonic neoplasms (2 papers); melanoma (2); adenoma (1); anaplastic thyroid cancer (1); bladder urothelial carcinoma (1); calcific aortic valve disease (1); differentiated thyroid carcinoma (1); esophageal squamous cell carcinoma (1); glioma (1); glomerulosclerosis (1); Hereditary breast cancer (1); Hyperglycemia (1); hyperphosphatemia (1); hyperplasia (1); injury (1); oesophageal cancers (1); oligodendroglioma (1); oral squamous cell carcinomas (1); osteosarcoma (1); prostate adenocarcinoma (1); prostate carcinoma (1); renal carcinoma (1); thymoma (1).